SHBG (sex hormone binding globulin)
Diseases named in the same sentence as SHBG in open-access papers (continued):
Sharing a sentence is not in itself a finding about the gene and the disease.
hypogonadism (continued). "This largely comes from high SHBG, which seems to play a central role in the pathogenesis of hypogonadism in this population." (PMID 33289905, 2021). "SHBG values were elevated in one third of patients, and higher in men with compensated hypogonadism." (PMID 33289905, 2021). "When also SHBG and cFT were assessed (Group B, 118 patients), overt hypogonadism was found in 22/118 (18.6%) patients." (PMID 33289905, 2021). "In particular, 39 studies provided information on the prevalence hypogonadism, and 13 on TT levels, whereas data on SHBG and fT were available in five and six studies, respectively." (PMID 34440836, 2021). "Our results from the UPOD portion of this study indicate that lower levels of testosterone in adult men who are being assessed for possible hypogonadism are consistently associated with lower levels of estradiol, PSA, SHBG, and LH." (PMID 30670838, 2020). "It is worth noting that obese hyperglycemic males enrolled in this study had hypogonadism (drop in testosterone and SHBG concentrations) and elevated levels of the estradiol hormone." (PMID 31816998, 2019). "It is suggested that assessment of cBT or free T (unbound to SHBG or albumin) is more appropriate than that of TT alone for diagnosing hypogonadism, particularly in the cancer setting." (PMID 31487803, 2019). "Our study is based on a single measurement of hormones and SHBG and lack information on symptoms of hypogonadism and/or gonadotropin levels." (PMID 30057912, 2018). "With regard to hormones in the pituitary-testis axis, the men with hypogonadism had significantly lower total T, free T, E2, SHBG and higher FSH levels." (PMID 26177638, 2015). "SHBG levels are easily affected by many conditions, so total testosterone measurements can therefore be misleading indicators of hypogonadism." (PMID 20518947, 2010). "Moreover, HIV-positive men are a special group of patients who can benefit from SHBG testing, as this parameter is important for the diagnosis of biochemical hypogonadism." (PMID 40427034, 2025). "Hypogonadism in men and its connection to SHBG are being widely researched." (PMID 40427034, 2025). "Nevertheless, interesting facts are known about how the SHBG concentration may relate to hypogonadism in females." (PMID 40427034, 2025). "To determine whether our constructed and validated GS could reveal disease associations in MVP ancestry groups, we conducted Cox proportional hazards analyses with the total testosterone GS, the SHBG GS, and the hypogonadism GRS." (PMID 40316537, 2025). "Not only age, but other co-occurring diseases may contribute to alterations in SHBG concentration in men with hypogonadism." (PMID 40427034, 2025). "Specifically, the research concerning women’s hypogonadism and SHBG is poorly studied." (PMID 40427034, 2025). "Also this study is limited by the use of TT to diagnose hypogonadism which can underestimate the prevalence of biochemical hypogonadism due to the possible rise in serum sex hormone binding globulin (SHBG) in HIV patients." (PMID 41035487, 2025). "Our findings are consistent with previous studies that also included SHBG levels, demonstrating that the prevalence of hypogonadism is underestimated when only TT levels are considered, compared to cFT accounting for SHBG, which can be elevated in these patients." (PMID 40982123, 2025). "A reduction in SHBG levels leads to a decrease in total testosterone, which could unjustly suggest hypogonadism, even if free testosterone levels remain normal." (PMID 40678315, 2025). "The univariate and multivariable generalized linear models were used to evaluate the effect of anthropometric characteristics, clinical comorbidities (expressed as CCI and mCCI), hormonal parameters (FSH, LH, SHBG, and FT), and hypogonadism on the IIEF 5 score." (PMID 37020191, 2023).
hypogonadism (continued). "It was recently suggested that SHBG testing could help evaluate infertile men, especially in the situation of hypogonadism, as SHBG binds androgens and estrogens and contribute to their bioavailability." (PMID 36303626, 2022). "In particular, increased SHBG serum levels are typically detected in HIV-infected men, leading to normal total testosterone serum levels in spite of actually low free testosterone levels, causing biochemical hypogonadism." (PMID 33807833, 2021). "Furthermore, in the European Male Aging Study, men diagnosed with late onset hypogonadism, with lower testosterone and SHBG levels and a higher waist circumference and BMI than the eugonadal men, also had lower estradiol levels." (PMID 33014416, 2020). "However, according to the ESE guidelines, gonadotropin, TT, and sexual hormone binding globulin (SHBG) for the determination of bioavailable testosterone must be assessed only in the presence of known signs/symptoms of hypogonadism." (PMID 32998364, 2020). "Additionally, mitotane increases hepatic synthesis of sex hormone-binding globulin (SHBG), which may result in hypogonadism related symptoms due to reduced free sex hormones levels." (PMID 40868483, 2025). "Many factors may contribute to hypogonadism in cirrhosis, including hepatic overproduction of SHBG, changed SHBG isoforms with different steroid-binding affinities, elevated prolactin levels, direct suppression of Leydig cell function by estrogens or increased estrogen receptors in the liver." (PMID 33515211, 2021). "Thus, the mere measurement of total testosterone could mask a condition of biochemical hypogonadism and the assay of SHBG for the calculation of free testosterone levels is required for the correct evaluation of the gonadal status in HIV men." (PMID 33807833, 2021). "Therefore, SHBG-Tg mice may be a more suitable animal model to study late-onset hypogonadism than ORX." (PMID 29343749, 2018). "Total testosterone levels might be normal with hypogonadism if the SHBG levels are increased." (PMID 26740862, 2016). "The use of total serum T alone may have resulted in an underestimation of the prevalence of biochemical hypogonadism since calculated free serum T has been suggested as more appropriate in the context of HIV due to the possible rise in serum SHBG in these patients." (PMID 22174826, 2011). "Serum testosterone significantly correlated with gonadotropins levels, prolactin, SHBG, and FTI scores in patients with hypogonadism before surgery." (PMID 39337013, 2024). "The estimation of calculated free testosterone (cFT) is considered useful in patients with conditions that alter SHBG levels and when the total T levels are close to the LLN to avoid the under/over-diagnosis of hypogonadism." (PMID 38132234, 2023). "The characteristic hormonal features of obese men, low blood testosterone and SHBG with normal LH and FSH, indicate a eugonadal state, better termed pseudo-hypogonadism." (PMID 35116001, 2021). "In conclusion, in this study we found that the rs1799941 polymorphism in young non-diabetic obese males with hypogonadism was related to SHBG levels and consequently could be determining the FT fraction according to the relationship present between FT and the rs1799941 polymorphism as well." (PMID 31370189, 2019). "We aimed to investigate the relationship between 25(OH)D levels and total and free testosterone (T), sex hormone binding globulin (SHBG), estradiol, and hypogonadism in Chinese men." (PMID 26177638, 2015). "Reduced Sex Hormone-Binding Globulin (SHBG) concentrations coupled to low testosterone levels and correlating to OSAS severity support a diagnosis of secondary hypogonadism." (PMID 20182553, 2010). "In contrast, within the hypogonadism group, the strongest correlations were observed between total testosterone and free testosterone (0.9), between LH and FSH (0.68), and total testosterone and SHBG (0.44)." (PMID 40647593, 2025).
hypogonadism (continued). "Near–absent serum SHBG influences calculated free testosterone, complicating the evaluation of suspected hypogonadism." (PMID 41281936, 2025). "Efavirenz may also contribute to male infertility by elevating sex hormone-binding globulin (SHBG) levels, which in turn induces hypogonadism." (PMID 39753908, 2025). "Based on the clinical/laboratory information and levels of SHBG, subjects with hypogonadism and other disorders were ruled out." (PMID 39982363, 2025). "Unfortunately, the absence of values of serum SHBG and free testosterone do not allow to fully evaluate the presence hypogonadism in this caseload." (PMID 37306894, 2024). "Firstly, our study was based on a single measuring of all gonadal hormones and SHBG, and information on symptoms of hypogonadism and/or gonadotropin levels was lacking." (PMID 38988998, 2024). "The calculated FT and FAI, which mainly depend on TT and SHBG, showed a significant decrease in the AZA group, which may be due to hypogonadism." (PMID 37049533, 2023). "In addition, we evaluated the changes in LH, SHBG, TT, and cFT levels after six months of ART administered in patients who showed overt hypogonadism (n=8)." (PMID 38269251, 2023). "Age, anthropometric parameters (BMI and WC), and hormone levels (testosterone, FT, and SHBG) were not statistically different between the two sub-groups of hypogonadism." (PMID 37020191, 2023). "In the study conducted by Liang and cols., in which they examined the relationship between hypogonadism symptoms and biochemical parameters in aging men, the IIEF-5 and AMS scales were used, and a significant correlation was observed between LH and sex hormone binding globulin and sexual functions." (PMID 36468923, 2023). "We previously showed that elevated SHBG levels are very common in HIV-infected men and might represent the primum movens of the compensated form of hypogonadism in these patients." (PMID 34460073, 2022). "Higher values of SHBG were especially found in men with compensated hypogonadism, even without reaching statistical significance when compared to hypogonadal men, probably due to the relatively small number of patients included." (PMID 33289905, 2021). "While we did not measure SHBG levels, we assessed free testosterone, where the prevalence of hypogonadism was not different among groups." (PMID 34077443, 2021). "Given that testosterone undergoes hepatic metabolization and its levels are influenced by circulating SHBG which is secreted by the liver, it has been hypothesized that NAFLD may play a key role in secondary hypogonadism." (PMID 31817436, 2019). "Fourth, diagnoses of hypogonadism and fatty liver, which could change sex steroid & SHBG production, were absent in NHANES." (PMID 35493382, 2022). "The total testosterone measurement alone could not correctly diagnose hypogonadism due to the concomitant increase in SHBG: free testosterone evaluation is therefore required, starting at least within 6 months of mitotane therapy." (PMID 34638485, 2021). "Neither measurement of SHBG and albumin, nor free-T calculation was available in patients with TT in “grey zone“ (264–300 ng/dl), which may have possibly impacted on the real prevalence of hypogonadism in the enrolled patients." (PMID 33063272, 2021). "HIV patients also tend to have higher levels of SHBG on average which may mask true hypogonadism if free testosterone is not tested, which underpins the importance of guideline adherence (Atan, Tuncel, Yesil, & Balbay, 2013; Martin, Benassayag, Amiel, Canton, & Nunez, 1992)." (PMID 29183245, 2018). "In accordance with that, SHBG concentration should always be performed in HIV-positive males to calculate free testosterone concentration and not omit biochemical hypogonadism." (PMID 40427034, 2025).
hypogonadism (continued). "The positive genetic correlation was observed for total testosterone with free testosterone and SHBG levels in the EUR ancestry groups, while negative genetic correlations were observed between total testosterone and hypogonadism in the EUR, AFR, and AMR ancestry groups." (PMID 40316537, 2025). "The difference in SHBG occurred at the limit of statistical significance in hypogonadal men (−13.26: −26.67; 0.15, p = 0.050), whereas only one study considered HIV-infected men without hypogonadism at baseline." (PMID 34440836, 2021). "Moreover, in both controls and KS patients, we did not use the free-testosterone index (testosterone/sex hormone-binding globulin [SHBG]), mainly adopted to confirm the clinical diagnosis of hypogonadism or to modulate the androgen treatment." (PMID 32865776, 2021).
prostate carcinoma (57 papers, 1993 to 2025). A carcinoma that arises from epithelial cells of the prostate gland. "HI and SHBG showed synergistic inverse associations with total prostate cancer risk with unclear mechanism." (PMID 38234143, 2024). "Hip size and sex hormone binding globulin showed synergistic inverse associations with total prostate cancer risk." (PMID 38234143, 2024). "These mutations can alter the binding capacity of SHBG, leading to reduced testosterone bioavailability and resulting in infertility, prostate cancer, or gonadal dysfunction." (PMID 39057081, 2024). "It is unclear, therefore, what is the mechanism underlying the synergistic inverse associations of HI and SHBG with total prostate cancer risk." (PMID 38234143, 2024). "Other GWAS traits associated at this locus comprise sex hormone-binding globulin levels, male-pattern baldness, fasting insulin, estradiol levels with the same effect direction and prostate cancer risk." (PMID 38233393, 2024). "While the data on SHBG in bone cancers and metastasis are sparse, one publication noted that in patients with prostate cancer, higher serum SHBG levels were associated with reduced bone mineral density and osteoporosis." (PMID 39684443, 2024). "Our findings are further in agreement with a previous study of prostate cancer risk in UK Biobank, reporting positive associations with FT and inverse with SHBG based on quintile categories and fewer cases." (PMID 38234143, 2024). "Male infertility, erectile dysfunction, prostate cancer, and several other male reproductive system diseases are all caused by reduced testosterone bioavailability due to its binding to SHBG." (PMID 36836833, 2023). "SHBG and total testosterone were inversely associated with overall prostate cancer in blood‐based analyses, with null associations in MR analysis." (PMID 35579976, 2022). "High SHBG levels are an independent risk factor for OP in men, especially in those with prostate cancer." (PMID 34239693, 2021). "In this article, we aimed to examine the associations of serum concentrations of IGF‐I, SHBG, total and free testosterone with prostate cancer incidence and mortality, using observational data from UK Biobank." (PMID 33252839, 2021). "Men with higher SHBG concentrations had a lower risk of prostate cancer, which is consistent with previous prospective studies." (PMID 33252839, 2021). "MR analyses of SHBG, total and free testosterone and prostate cancer risk using these datasets have recently been published." (PMID 33252839, 2021). "Men with higher free testosterone had an increased risk of prostate cancer, while men with higher SHBG had a decreased risk." (PMID 33252839, 2021). "Accordingly, low SHBG, T, and other sex steroids in community-dwelling middle-aged to elderly men and androgen deprivation therapy, as in the case of prostate cancer treatment, were associated with a higher incidence of T2DM and cardiovascular diseases." (PMID 31817436, 2019). "Higher expression of SHBG in prostate cancer tissue is associated with poor clinicopathological features suggesting a role in prostate cancer progression, perhaps due to prolonged expression of androgen responsive genes." (PMID 27990161, 2016). "HI and SHBG were associated inversely with prostate cancer risk, more strongly when both were high." (PMID 38234143, 2024). "HI and SHBG showed synergistic inverse associations with prostate cancer risk." (PMID 38234143, 2024). "Amongst males, an increased risk of prostate cancer was observed for bioavailable testosterone (OR = 1.22, 95% CI: 1.08, 1.37) but not in relation to total testosterone (OR = 0.97, 95% CI: 0.86, 1.07), or SHBG (OR = 0.91, 95% CI: 0.76, 1.09)." (PMID 35061662, 2022). "Third, changes in certain hormones, including testosterone, sex hormone-binding globulin, and leptin, may affect the risk of prostate cancer." (PMID 27652121, 2016).